PDPN (podoplanin)
Description:
Mediates effects on cell migration and adhesion through its different partners. During development plays a role in blood and lymphatic vessels separation by binding CLEC1B, triggering CLEC1B activation in platelets and leading to platelet activation and/or aggregation. Interaction with CD9, on the contrary, attenuates platelet aggregation induced by PDPN. Through MSN or EZR interaction promotes epithelial-mesenchymal transition (EMT) leading to ERZ phosphorylation and triggering RHOA activation leading to cell migration increase and invasiveness. Interaction with CD44 promotes directional cell migration in epithelial and tumor cells. In lymph nodes (LNs), controls fibroblastic reticular cells (FRCs) adhesion to the extracellular matrix (ECM) and contraction of the actomyosin by maintaining ERM proteins (EZR; MSN and RDX) and MYL9 activation through association with unknown transmembrane proteins. Engagement of CLEC1B by PDPN promotes FRCs relaxation by blocking lateral membrane interactions leading to reduction of ERM proteins (EZR; MSN and RDX) and MYL9 activation (By similarity). Through binding with LGALS8 may participate in connection of the lymphatic endothelium to the surrounding extracellular matrix. In keratinocytes, induces changes in cell morphology showing an elongated shape, numerous membrane protrusions, major reorganization of the actin cytoskeleton, increased motility and decreased cell adhesion. Controls invadopodia stability and maturation leading to efficient degradation of the extracellular matrix (ECM) in tumor cells through modulation of RHOC activity in order to activate ROCK1/ROCK2 and LIMK1/LIMK2 and inactivation of CFL1. Required for normal lung cell proliferation and alveolus formation at birth (By similarity). Does not function as a water channel or as a regulator of aquaporin-type water channels. Does not have any effect on folic acid or amino acid transport (By similarity).
Synonyms: Gp36; T1A; T1A-2; Gp38; aggrus; GP40; PA2.26; D2-40; HT1A-1; OTS8; T1A2; TI1A
Tractability: Antibody: UniProt places it where antibodies can reach, with high confidence; its Gene Ontology location is reachable by antibodies, with high confidence; UniProt predicts a signal peptide or a membrane-spanning region; the Human Protein Atlas places it where antibodies can reach.
Gene: Protein-coding gene on chromosome 1 (13,583,465 to 13,617,957, forward strand). Ensembl gene ENSG00000162493.
Subcellular location: Membrane (Podoplanin); Cell projection, lamellipodium membrane; Cell projection, filopodium membrane; Cell projection, microvillus membrane; Cell projection, ruffle membrane; Membrane raft; Apical cell membrane; Basolateral cell membrane; Cell projection, invadopodium; Cytoplasm, cytosol (29kDa cytosolic podoplanin intracellular domain)
Subcellular location (Human Protein Atlas): Plasma membrane; Cell Junctions; Mitochondria
Pathways (Reactome):
Hemostasis: GPVI-mediated activation cascade
Reproduction: Specification of primordial germ cells
Gene Ontology:
Molecular function: chemokine binding; protein binding; protein-folding chaperone binding; signaling receptor binding; amino acid transmembrane transporter activity; folic acid transmembrane transporter activity
Biological process: positive regulation of cell migration; positive regulation of epithelial to mesenchymal transition; positive regulation of extracellular matrix disassembly; positive regulation of platelet aggregation; regulation of lamellipodium morphogenesis; Rho protein signal transduction; wound healing, spreading of cells; actin-mediated cell contraction; amino acid transport; cell adhesion; cell migration; folic acid transport; lung development; lymph node development; lymphangiogenesis; lymphatic endothelial cell fate commitment; negative regulation of apoptotic process; negative regulation of cell population proliferation; platelet activation; regulation of myofibroblast contraction; regulation of substrate adhesion-dependent cell spreading; signal transduction
Cellular component: apical plasma membrane; basolateral plasma membrane; cell junction; cell projection; cytoplasmic vesicle; cytosol; filopodium membrane; lamellipodium membrane; leading edge of lamellipodium; membrane; membrane raft; microvillus membrane; plasma membrane; ruffle membrane; tetraspanin-enriched microdomain; filopodium; lamellipodium; ruffle
Genetic constraint (gnomAD): Loss-of-function variants: 4 observed, 13.29 expected, observed/expected ratio (o/e) 0.3, 90% interval 0.15 to 0.69. The upper end of that interval is the gene's LOEUF score, 0.69, which puts it in group 2 of 6, group 1 being the genes least tolerant of losing a copy. Missense variants: 140 observed, 153.3 expected, observed/expected ratio (o/e) 0.91, 90% interval 0.8 to 1.05. Synonymous variants: 54 observed, 56.29 expected, observed/expected ratio (o/e) 0.96, 90% interval 0.77 to 1.2.
Homologues: Orthologues: chimpanzee PDPN (99% identical), macaque PDPN (93% identical), dog PDPN (64% identical), pig PDPN (62% identical), rabbit PDPN (56% identical), rat Pdpn (45% identical), mouse Pdpn (44% identical).
Diseases named in the same sentence as PDPN in open-access papers:
PDPN is named in the same sentence as 374 diseases in open-access papers, as found by Europe PMC text mining. Sharing a sentence is not in itself a finding about the gene and the disease. The quoted sentences say what the papers report.
breast carcinoma (91 papers, 2005 to 2026). "In breast cancer, a subset of tumor-associated macrophages expresses podoplanin (PDPN), which interacts with Gal-8 on lymphatic ECs, promoting the formation of new lymphatic vessels and the migration of cancer cells through the lymphatic system." (PMID 40136652, 2025). "The upregulation of PDPN has been observed in a variety of human cancers, including brain cancer, breast cancer, lung cancer, and mesothelioma, and is associated with poor prognosis." (PMID 40693815, 2025). "In breast cancer, a tumor-associated macrophage subset expressing podoplanin (PDPN) is involved in the attachment of this macrophage subset to lymphatic ECs." (PMID 38426109, 2024). "In one study of patients with breast cancer, the association of PDPN-expressing macrophages with tumor lymphatic vessels correlated with increased lymph node and distant organ metastasis." (PMID 37801190, 2023). "The process of lymphatic metastasis was proved to be associated with podoplanin-expressing macrophages in breast cancer (BC)." (PMID 37744272, 2023). "The process of lymphatic metastasis in breast cancer has been found to be associated with a specific type of macrophages expressing podoplanin." (PMID 37744272, 2023). "Another group found that among mammary tumor-infiltrating immune cells, the cells that expressed the highest levels of PDPN were tumor-associated macrophages." (PMID 37801190, 2023). "The beneficial targeting of macrophage emigration to lymph nodes is dependent on the disease, as the association of podoplanin+ macrophages with tumour lymphatic vessels in mammary tumour model correlates with increased lymph node and distant organ metastasis." (PMID 34163489, 2021). "While high CALB2 or PDPN expression in several other carcinomas, including breast cancer, was associated with a poor prognosis, the OS of other cancers, in particular hematologic malignancies, showed the opposite association." (PMID 32533757, 2020). "The inhibition of lymphangiogenesis employing PDPN-tk mice supports that breast-cancer–associated LN and lung metastasis is in part relying upon dissemination of cancer cells via lymphatic vessels." (PMID 30592710, 2018). "The question remains as to how our experimental data can be correlated with previous clinical data showing an association between the presence of podoplanin-positive cancer-associated fibroblasts and progression of breast cancer." (PMID 28938000, 2017). "In our previous studies we showed that in breast cancer podoplanin-positive cancer-associated fibroblasts correlated positively with tumor size, grade of malignancy, lymph node metastasis, lymphovascular invasion and poor patients’ outcome." (PMID 28938000, 2017). "In mammary tumors, cancer associated fibroblasts (CAFs) which constitute a major cell component of the stroma, express PDPN but little is known about its mechanism of expression and modulation." (PMID 28416768, 2017). "In breast cancer, podoplanin expression by CAFs was associated with increased breast tumor size, histologic grade, lymph node metastasis, lymphovascular invasion and worse disease-free and overall survival." (PMID 26828520, 2016). "In another study of 156 invasive ductal breast cancer samples, podoplanin expression in stromal breast cancer-associated fibroblasts was associated with higher grade and triple-negative breast cancer." (PMID 26828520, 2016). "Antibodies to podoplanin have recently been used to demonstrate that high lymphatic microvessel density is associated with lymph node metastasis in human breast cancer." (PMID 18325094, 2008). "In addition, podoplanin-expressing macrophages have been shown to be associated with lymphatic metastasis of breast cancer." (PMID 39273429, 2024).
breast carcinoma (continued). "The levels of Interleukin 24 (IL-24), a cytokine that inhibits tumor progression, and its receptor, the IL-24 receptor (IL-24R), are found to be reduced in breast cancer samples and are associated with increased levels of lymph-specific markers, such as podoplanin, PROX1, and LYVE-1." (PMID 35885529, 2022). "Therefore, CD68, Sema7A, and PDPN are associated with poor prognosis of breast cancer patients with lymphatic metastasis." (PMID 35155237, 2022). "In addition, recent studies have also implicated macrophages expressing lymphatic-associated markers, including Lyve-1 and podoplanin, in mammary tumor metastasis through modulation of lymphatics." (PMID 32479261, 2020). "In addition, several reports linked podoplanin expression in CAFs of prostate, bladder, ovary, pancreas, and breast carcinomas with intratumoral lymphangiogenesis, lymph node metastasis, and lymphatic invasion." (PMID 30736372, 2019). "Therefore, the present study was undertaken to assess if podoplanin expressed by fibroblasts can affect malignancy-associated properties of breast cancer cells." (PMID 28938000, 2017). "First, CLEC-2 functions as a high-affinity receptor for podoplanin, a transmembrane glycoprotein that is frequently upregulated in various malignancies, including advanced-stage breast cancer." (PMID 41209555, 2025). "PDPN promotes fibroblast migration and accelerates endothelial cell pseudotube formation, contributing to breast cancer development and metastasis." (PMID 40230452, 2025). "Macrophage-specific PDPN conditional knockout mice showed reduced lymph angiogenesis and lymph invasion in breast cancer." (PMID 39780187, 2025). "PDPN-positive CAFs are associated with low IL-2 activity and trastuzumab resistance in patients with HER2-positive breast cancer." (PMID 40303301, 2025). "This has been demonstrated in a particular mouse model with breast carcinoma cells, or with the antibody NZ-1 anti-PDPN for lung metastatization of CHO-expressing human (h)PDPN, or using point-mutated hPDPN-expressing CHO cells." (PMID 40677711, 2025). "PDPN has been previously shown to be upregulated in a variety of cancers including breast cancer, lung cancer, pancreatic cancer." (PMID 40842027, 2025). "Like POSTN, PDPN is used in humans in the diagnosis of a variety of tumours, and its presence has also been found in CAFs and tumour cells, for example in breast cancer, oesophageal cancer, and lung adenocarcinoma." (PMID 41361308, 2025). "Studies in a mouse model have shown that the removal of PDPN-expressing macrophages or inhibition of Gal-8 reduces metastatic potential in breast cancer." (PMID 40136652, 2025). "Experimental removal of PDPN-expressing macrophages or inhibition of Gal-8 significantly reduces tumor metastasis in mouse breast cancer models." (PMID 38426109, 2024). "A previous breast cancer study showed that PDPN+ macrophages also localize to the proximity of tumor lymphatics and induce lymphangiogenesis and lymphoinvasion." (PMID 39080406, 2024). "Further, PDPN+ macrophages are involved in extracellular matrix remodeling near lymphatics and promote lymphangiogenesis, and their deletion results in delayed breast cancer invasion." (PMID 38426622, 2024). "Further studies, including prospective validation, are necessary to unravel the biological background of D2-40/ podoplanin variations of the sinus endothelium and its full clinical relevance for human beings, particularly for breast cancer patients." (PMID 36693068, 2023). "In breast cancer, the S100A4/PDPN expression ratio in CAFs is associated with disease outcomes across subtypes." (PMID 37894446, 2023). "Studies from multiple cancer biopsies, cultured human breast cancers and mouse model of carcinogenesis indicates that increased expression of podoplanin renders tumor cells motile and invasive, through actin cytoskeleton remodelling." (PMID 36247509, 2022).
breast carcinoma (continued). "Sema7A promotes macrophages podoplanin (PDPN) expression, migration, and adhesion of the lymphatic epithelial cell, resulting in breast cancer lymphatic metastasis." (PMID 35155237, 2022). "Underlining the functional heterogeneity of CAFs, they report a similar mechanism in breast cancer where PDPN+ CAFs significantly inhibited the proliferation of CD4+ and CD8+ T cells in co-culture via production of NO while PDPN- CAFs do not." (PMID 35479076, 2022). "Podoplanin in CAFs is up-regulated in a variety of tumors, such as breast cancer, lung cancer, and pancreatic cancer." (PMID 34566887, 2021). "CAF markers that have been associated with promotion of breast cancer tumor growth through several experiments include α-SMA, FAP, PDGFR-α, PDGFR-β, CD29, neural/glial antigen 2 (NG2), FSP1, vimentin, and podoplanin (PDPN)." (PMID 33808627, 2021). "In particular, podoplanin is the marker usually used to investigate the invasion of lymphatic vessels by breast cancer cells." (PMID 34833492, 2021). "Podoplanin-expressing macrophages (PoEMs) are located near lymphatic vessels in murine breast cancer." (PMID 33783686, 2021). "This is highly relevant in diseases describing platelet-bound podoplanin-positive macrophages such as atherosclerosis, rheumatoid arthritis, and breast cancer." (PMID 34163489, 2021). "Podoplanin+S100A4+PDGF-Rα+ fibroblasts are present in bone metastasis sites of human breast cancer patients." (PMID 33050237, 2020). "We and others reported that podoplanin is a novel component of invadopodia in breast cancer and SCC cells." (PMID 30736372, 2019). "Cueni and co-workers, using a human breast carcinoma xenograft model, found that podoplanin expression enhanced lymphangiogenesis and metastasis to regional lymph nodes without affecting primary tumor growth." (PMID 30736372, 2019). "It is well recognized that podoplanin expression is correlated with a poor prognosis and tumor malignancy in lung carcinomas, oral squamous cell carcinomas, and breast cancers." (PMID 30279963, 2018). "Despite a significant suppression of lymphangiogenesis, the growth of orthotopic 4T1 mammary tumors in GCV-treated PDPN-tk mice was unchanged when compared with GCV-treated WT control mice." (PMID 30592710, 2018). "In our studies, the vascular density in the mammary tumors was unchanged upon depletion of PDPN+ cells." (PMID 30592710, 2018). "It was found that the numbers of migrating fibroblasts overexpressing podoplanin were similar to the numbers of fibroblasts overexpressing podoplanin co-cultured with breast cancer cells." (PMID 28938000, 2017). "In our previous studies we showed that in breast cancer PDPN-positive CAFs correlated positively with tumor size, grade of malignancy, lymph node metastasis, lymphovascular invasion and poor patients’ outcome." (PMID 28938000, 2017). "According to transfection studies in human MCF7 breast cancer cells, PDPN expression results in morphological changes, induction of migratory phenotypes with a significant decrease in cellular stress fibers, and an increase in filopodia-like protrusions." (PMID 24354864, 2013). "For example, PDPN expression is strongly induced in about 40% of breast cancers, 50% of oral cancers, and 80% of skin cancers." (PMID 22844530, 2012). "In the present study, we compared the expression of the lymphatic endothelium-specific markers Prox-1, LYVE-1 and podoplanin in metastatically involved and uninvolved LNs of patients with breast cancer." (PMID 17088912, 2006). "We investigated the presence and extent of lymphangiogenesis in LN metastases of breast cancer using the podoplanin antibody." (PMID 17088912, 2006). "In the murine 4T1 breast cancer model, immunofluorescence co-staining with the lymphatic-specific marker podoplanin (PDPN) and FAT1 revealed a significant reduction in FAT1 fluorescence intensity within tumor-associated lymphatic vessels compared to those in normal mammary tissue." (PMID 41230499, 2025).